CHI3L1 (chitinase 3 like 1)
Diseases named in the same sentence as CHI3L1 in open-access papers (continued):
Sharing a sentence is not in itself a finding about the gene and the disease.
lung disease (16 papers, 2011 to 2025). "The interaction between CHI3L1 and IL‐13Rα2 could promote lung diseases associated with Hermansky–Pudlak syndrome." (PMID 34758182, 2022). "Reportedly, elevated Chi3l1 levels are strongly linked with CF pathology in both pediatric and adult patients with CF-related lung disease, and neutrophils are considered a potential source of increased Chi3l1." (PMID 39769202, 2024). "While the correlation between CHI3L1(YKL40) expression and COPD has been observed, further research is needed to elucidate the underlying mechanisms of CHI3L1(YKL40) in COPD pathogenesis and its potential as a therapeutic target for this complex lung disease." (PMID 38543093, 2024). "In recent studies using transgenic or KO mice of Chi3l1 in various animal models of lung diseases showed an essential role of Chi3l1 in the pathogenesis of inflammation and tissue remodeling." (PMID 29403003, 2018).
pneumonia (16 papers, 2007 to 2025). An acute, acute and chronic, or chronic inflammation focally or diffusely affecting the lung parenchyma, caused by an infection in one or both of the lungs (by bacteria, viruses, fungi, or mycoplasma.). "Higher levels of CRP, PCT and CHI3L1 were associated with increased odds of end-point pneumonia compared to normal CXR." (PMID 26366571, 2015). "Plasma levels of inflammation-associated proteins CRP and CHI3L1 were significantly higher in children with end-point pneumonia compared to the other groups." (PMID 26366571, 2015). "Future studies should also evaluate whether common childhood co-infections associated with elevated CHI3L1, such as pneumonia and schistosomiasis, affect the accuracy of CHI3L1 as a prognostic indicator in malaria infection." (PMID 25047113, 2014). "Many studies have reported that Chi3l1 serves as a useful biomarker for assessing the severity and prognosis of multiple inflammatory pulmonary diseases, including pneumonia, lung injury, and lung fibrosis." (PMID 39769202, 2024). "CHI3L1 levels are increased in chronic inflammatory conditions and acute infections such as pneumonia, meningitis, and sepsis, and often correlate with disease severity and prognosis." (PMID 25047113, 2014). "Pneumonia, a common acute respiratory infection, is closely related to Chi3l1 levels." (PMID 39769202, 2024). "Compared to children with normal x-ray, children with end-point pneumonia had significantly higher C-reactive protein, procalcitonin and Chitinase 3-like-1, while those with other infiltrates had elevated procalcitonin and von Willebrand Factor and decreased soluble Tie-2 and endoglin." (PMID 26366571, 2015). "We identified CHI3L1 as a novel marker in pediatric pneumonia." (PMID 26366571, 2015). "In adults, serum CHI3L1 levels were elevated in streptococcal pneumonia compared to pneumonia of unknown etiology and healthy controls." (PMID 26366571, 2015). "This may be due to differential pathway engagement: CHI3L1 exerted its major effects in the pneumonia model by regulating the NRLP3 inflammasome, while involvement of the classical NRLP3 inflammasome in ECM pathogenesis is doubtful." (PMID 25047113, 2014). "Whether CHI3L1 confers protection in human pneumonia warrants further investigation." (PMID 26366571, 2015). "Plasma levels of CRP, PCT, and CHI3L1 were elevated in end-point pneumonia compared to non-end-point pneumonia and significant in ROC curve analysis." (PMID 26366571, 2015). "Several cytokines (CHI3L1, IL-1Rα, IL-6, G-CSF, MCP-1, and MIP-1α) were elevated in severe pneumonia cases, regardless of disease etiology." (PMID 41488910, 2025).
sarcoidosis (16 papers, 2009 to 2025). Sarcoidosis is a multisystemic disorder of unknown cause characterized by the formation of immune granulomas in involved organs. "The effects of rs7515776 polymorphism of the CHI3L1 gene and YKL-40 levels on the course of the disease were investigated in sarcoidosis patients." (PMID 39045955, 2024). "A variant (-329 G/A polymorphism) in the chitinase 3 like 1 gene (CHI3L1) contributes to interindividual variations of YKL-40 levels but does not influence sarcoidosis disease susceptibility or severity." (PMID 30154391, 2018). "Similar to NL and NXG, sarcoidosis lesional macrophages upregulated expression of the macrophage polarization marker genes MARCO, FCGR3A, NR1H3; the ECM-encoding gene FN1; the protease-encoding gene CTSS; and genes associated with inflammation, S100A8 and CHI3L1." (PMID 39989459, 2025). "A study investigating various polymorphisms of CHI3L1 in relation to sarcoidosis has found that the CHI3L1 -329 G/A polymorphism (rs10399931) contributes to interindividual variations of YKL-40 levels in patients with sarcoidosis but does not influence sarcoidosis susceptibility or disease severity." (PMID 19568425, 2009).
encephalitis (15 papers, 2010 to 2026). An acute inflammatory process affecting the brain parenchyma. "In the present study, through a combination of proteomic analysis, molecular assays, and histological experiments, we demonstrated that CHI3L1 expression is significantly upregulated during the course of anti‐NMDAR encephalitis." (PMID 41489316, 2026). "In light of these findings, our results show that CHI3L1 expression is markedly elevated in anti‐NMDAR encephalitis, accompanied by signs of disrupted hippocampal neurogenesis and a significant upregulation of CRTH2 in the hippocampus." (PMID 41489316, 2026). "Specifically, cerebrospinal fluid levels of Chi3l1 are increased in both anti-gamma-aminobutyric-acid-B receptor (GABAbR) encephalitis and anti-N-methyl-D-aspartate receptor (NMDAR) encephalitis." (PMID 39769202, 2024). "Patients with anti-LGI1 encephalitis had significantly higher CHI3L1 levels in the serum and CSF than controls." (PMID 36685530, 2022). "The present study, that patients with anti-LGI1 encephalitis had elevated serum and CSF CHI3L1 levels." (PMID 36685530, 2022). "One study has shown that CHI3L1 levels are significantly elevated in the CSF of patients with anti-LGI1 encephalitis." (PMID 36685530, 2022). "CHI3L1 levels in CSF and serum were highly elevated in patients with anti-LGI1 encephalitis at admission compared those with the controls.(At admission, patients with anti-LGI1 encephalitis had elevated CHI3L1 levels in the CSF and serum)." (PMID 36685530, 2022). "Some studies have shown that patients with anti-N-methyl-d-aspartate receptor (NMDAR) encephalitis have higher CHI3L1 levels in the cerebrospinal fluid (CSF) than viral encephalitis patients or healthy people." (PMID 36685530, 2022). "In our previous study, longitudinal analysis of CSF of SIV-infected macaques showed that CHI3L1 concentrations in the CSF increased between 2 to 8 weeks before terminal encephalitis." (PMID 20540736, 2010). "CHI3L1 transcription was more pronounced in diseases with a more pronounced inflammatory nature like encephalitis and MS." (PMID 20540736, 2010). "We have previously reported that CHI3L1 serves as a CSF biomarker for the development of encephalitis after SIV or HIV infection." (PMID 20540736, 2010). "In addition, Chi3l1 is a promising biomarker for various types of viral encephalitis, such as tick-borne encephalitis (TBE) and human immunodeficiency virus encephalitis (HIVE)." (PMID 39769202, 2024). "However, few studies have documented serum and CSF CHI3L1 levels in patients with anti-LGI1 encephalitis." (PMID 36685530, 2022). "Thus, we investigated the changes in serum and CSF CHI3L1 levels in anti-LGI1 encephalitis patients and their relationship with severity and prognosis." (PMID 36685530, 2022). "Next, we evaluated whether CHI3L1 levels could be used to identify anti-LGI1 encephalitis patients using ROC curves." (PMID 36685530, 2022). "Other mediators of neuroinflammation have been found to be elevated in the serum and CSF of patients with anti-NMDAR encephalitis and to correlate with their functional status such as chitinase-3-like 1 (CHI3L1), osteopontin (OPN), pentraxin 3 (PTX3), CD40L, CD146, and CD138." (PMID 34884930, 2021). "CSF studies have also found elevated CHI3L1 in patients with purulent meningitis and encephalitis." (PMID 20540736, 2010). "We quantified CHI3L1 in CSF (n =30) and serum samples (n =30) from patients with anti-LGI1 encephalitis (n =35), and controls (n = 22) using an ELISA assay." (PMID 36685530, 2022). "Additionally, CHI3L1 has demonstrated promising potential for identifying biomarkers for tick-borne encephalitis (TBE) and West Nile virus (WNV) encephalitis." (PMID 37834128, 2023). "(CSF CHI3L1 levels are correlated with the severity and prognosis of anti-LGI1 encephalitis)." (PMID 36685530, 2022). "CHI3L1 level in CSF is correlated with the severity and prognosis of anti-LGI1 encephalitis." (PMID 36685530, 2022).
encephalitis (continued). "CSF CHI3L1 levels were significantly elevated in MS patients, however, HIV-infected individual with high viral load showed higher CSF concentration consistent with the observation that neuroinflammation in encephalitis is more robust than in unselected MS." (PMID 20540736, 2010). "Interestingly, anti-LGI1 encephalitis patients who presented with only FBDS at admission (n = 6) had significantly lower CSF CHI3L1 levels than those without FBDS symptoms (n = 24, p = 0.029)." (PMID 36685530, 2022).
pancreatic cancer (15 papers, 2009 to 2025). "For instance, CHI3L1 has been implicated in reducing the response of pancreatic cancer cells to gemcitabine." (PMID 38835347, 2024). "This Th2 phenotype can be induced either by CAF-secreting Chi3L1, or by orientating DCs to secrete Th2 chemokines, such as IL-13, in breast and pancreatic cancers, respectively." (PMID 33066357, 2020). "Three markers, CA19-9, OPN and CHI3L1, measured in multiplex were found to have superior sensitivity for pancreatic cancer vs. CA19-9 alone (93% vs. 80%)." (PMID 20003342, 2009). "A multiplex panel assaying CA19-9, OPN and CHI3L1 in plasma improves accuracy of pancreatic cancer diagnosis." (PMID 20003342, 2009). "Although the combination of CA19-9, OPN, and CHI3L1 improves the diagnostic accuracy compared to CA19-9 alone, our study was limited to patients with locally advanced pancreatic cancer." (PMID 20003342, 2009). "Importantly, a recent study verified that human monoclonal CHI3L1 neutralizing antibodies (nAbs) inhibited the tumor growth as well as mitigated fibrosis, angiogenesis and restored immunostimulatory functions in a pancreatic cancer orthotopic mice model." (PMID 39225813, 2024). "Importantly, pentoxifylline reversed drug resistance induced by CHI3L1 in pancreatic cancer cells." (PMID 38835347, 2024). "M2 differentiation is induced by CAF-secreted molecules such as Chitinase 3 Like 1 (Chi3L1), C-X-C motif chemokine 12 (CXCL12) and interleukin 6 (IL-6) in breast, prostate and pancreatic cancers, respectively." (PMID 33066357, 2020). "In our study, lower baseline CHI3L1 levels were observed in patients with CR/PR/SD (47.4 ng/ml) compared to PD patients (64.7 ng/ml), suggesting that plasmatic CHI3L1 level may be a predictive biomarker for VT1021 in patients with GBM and pancreatic cancer." (PMID 38773224, 2024).
schizophrenia (14 papers, 2010 to 2025). A major psychotic disorder characterized by abnormalities in the perception or expression of reality. "According to a multicenter case–control study and meta-analysis, genetic variants within the Chi3l1 gene exhibit ethnic heterogeneity and confer susceptibility to schizophrenia among Asian populations." (PMID 39769202, 2024). "On the other hand, Chi3l1 has been regarded as a schizophrenia susceptibility gene, a mediator of stress-induced cellular responses." (PMID 22369239, 2012). "Moreover, transcript expression of the schizophrenia susceptibility gene Chi3l1 is regulated by cis-variation in lymphoblasts, while polymorphisms within the promoter region of Chi3l1 significantly correlate with this allelic imbalance." (PMID 39769202, 2024). "An association is also found between schizophrenia and haplotypes within the promoter region of the CHI3L1 gene suggesting that polymorphisms in an area starting from base pair position -180 could have functional properties." (PMID 21714862, 2011). "Moreover, two genetic studies claimed that variants in the promoter of CHI3L1 are associated with susceptibility to schizophrenia." (PMID 20540736, 2010). "Schizophrenia is a common and complex psychiatric disease in which Chi3l1 levels are increased in the hippocampus and prefrontal cortex regions of patients." (PMID 39769202, 2024). "Inflammation related genes including S100A8, S100A9 and CHI3L1 are elevated in the hippocampus in schizophrenia and perivascular macrophages (CD163+) have been identified in the lumen of blood vessels and surrounding the endothelial cells in at least one schizophrenia hippocampus." (PMID 30214039, 2020). "For example, ANK3 has been associated with mental retardation, SLC45A1 with intellectual developmental disorder, and CHI3L1 with schizophrenia, suggesting that differential methylation data may help reveal novel genetic variations that associate with AD." (PMID 32539856, 2020). "Overall, our results showed only occasional CHI3L1 positive cells in schizophrenia." (PMID 20540736, 2010). "However, a more recent study failed to confirm a genetic association between CHI3L1 and schizophrenia in Japanese and Chinese populations." (PMID 20540736, 2010).
brain tumor (13 papers, 2008 to 2026). "A combination of anti- CHI3L1 neutralizing antibody and irradiation can synergistically inhibit tumor vascularization and progression in xenografted brain tumor models." (PMID 26452028, 2015). "To test the direct involvement of STAT3 pathway activation in the NF-κB pathway downstream of CHI3L1 action, we used WP1066, a selective inhibitor of STAT3 phosphorylation currently used in clinical trials for pediatric and adult brain tumors." (PMID 41480772, 2026).
Cirrhosis (13 papers, 2010 to 2025). A chronic disorder of the liver in which liver tissue becomes scarred and is partially replaced by regenerative nodules and fibrotic tissue resulting in loss of liver function. "The results in our study showed that when patients with advanced fibrosis (F3) were compared to those with significant fibrosis (F2) and cirrhosis (F4), serum CHI3L1 had the highest diagnostic accuracy for F3 at an early age." (PMID 35360517, 2022). "In the second year, the APRI, FIB‐4 and serum CHI3L1 levels in the non‐cirrhosis group decreased to levels similar with those of CHB patients." (PMID 38380526, 2024). "Six articles reported on diagnosing cirrhosis (F = 4) using serum CHI3L1, with a total of 907 patients of mean ages from 39.0 to 52.2 years." (PMID 35360517, 2022). "Conversely, in cirrhosis group, the APRI, FIB‐4 and serum CHI3L1 levels were higher than those in CHB patients for most of the follow‐up period." (PMID 38380526, 2024). "The upregulated genes between cirrhosis and healthy included GSN, COL4A4, CHI3L1, and GLIS2." (PMID 40489530, 2025). "Throughout the long‐term follow‐up, patients with cirrhosis consistently presented higher levels of APRI, FIB‐4, and serum CHI3L1 compared to those without cirrhosis (p < 0.05)." (PMID 38380526, 2024). "No potential publication bias was found for serum CHI3L1 in the diagnosis of significant fibrosis, advanced fibrosis, or cirrhosis, and posttest probability was moderate." (PMID 35360517, 2022). "Similarly, the posttest probabilities were 59% and 47% when serum CHI3L1 was positive for advanced fibrosis and cirrhosis diagnosis, respectively, and 4% and 6% when the results were negative for advanced fibrosis and cirrhosis diagnosis." (PMID 35360517, 2022).
interstitial lung disease (13 papers, 2017 to 2024). A diverse group of lung diseases that affect the lung parenchyma. "CHI3L1 plays a significant role in tissue inflammation and remodeling and has been implicated in the pathogenesis of granulomatous and fibrotic interstitial lung diseases." (PMID 32528988, 2020). "YKL-40, also known as chitinase 3-like-1, and Krebs von den Lungen-6 (KL-6) are two promising biomarkers that may play an important role in the diagnosis and prognosis of patients with interstitial lung diseases." (PMID 36975498, 2023).
psoriasis (13 papers, 2017 to 2025). An autoimmune condition characterized by red, well-delineated plaques with silvery scales that are usually on the extensor surfaces and scalp. "All in all, CHI3L1 represents a potential biomarker in several pathologies, including rheumatic diseases, such as psoriasis, psoriatic arthritis, RA, and OA." (PMID 34208590, 2021). "Through PubMed search, a total of 11 studies were found to discuss the relationship between psoriasis and YKL-40 (chitinase-3-like protein 1, CHI3L1, human cartilage glycoprotein-39) 64-74." (PMID 35813465, 2022). "Chi3l1 serum levels are significantly correlated with the 28-joint disease activity score (DAS 28), body surface area (BSA), and psoriasis area and severity index (PASI), thereby contributing to diagnosing and monitoring the severity of joint involvement in patients with psoriatic arthritis." (PMID 39769202, 2024). "Chi3l1 levels are largely elevated in patients with psoriatic arthritis but not in those with psoriasis." (PMID 39769202, 2024). "Then, chitinase-3-like protein 1 (CHI3L1) and MMP10 distinguished psoriasis from psoriatic arthritis not undergoing systemic therapy and, in the presence of onychopathy, MMP8 levels were higher in psoriasis than in psoriatic arthritis." (PMID 31717649, 2019).
acute kidney injury (12 papers, 2014 to 2025). Sudden and sustained deterioration of the kidney function characterized by decreased glomerular filtration rate, increased serum creatinine or oliguria. "Urine or plasma Chi3l1 can act as valuable noninvasive biomarkers for acute kidney injury (AKI); for example, the levels of urinary Chi3l1 in patients with stage Ι AKI (9.13 ± 1.22 ng/mL), stage ΙΙ AKI (11.30 ± 1.54 ng/mL), and stage ΙΙΙ AKI (13.13± 1.16 ng/mL) continue to increase." (PMID 39769202, 2024). "One potential biomarker of acute kidney injury is chitinase-3 like 1 protein (CH3L1 YKL-40, HCgp39)." (PMID 31554244, 2019). "A translational study in renal transplantation suggested YKL-40, a chitinase 3-like-1 gene product, plays an important role in acute kidney injury (AKI) and repair, but data are lacking about this protein in urine from native human kidneys." (PMID 25128003, 2014). "Chitinase-3-like 1 (CHI3L1) is a glycoprotein elevated in paediatric severe malaria, and an emerging urinary biomarker of acute kidney injury (AKI)." (PMID 29448936, 2018).
amyloid (12 papers, 2016 to 2025). "In a 5×FAD mouse model of AD, astrocyte-specific knockout of Chi3l1 can reduce the amyloid plaque burden and restore memory functions." (PMID 39769202, 2024). "Thus, the upregulation of CHI3L1 suppresses microglial Aβ and astrocyte phagocytosis and accelerated amyloid plaque formation, which contributes to the progression of AD." (PMID 38667293, 2024). "Total numbers of amyloid plaque and NFTs did not correlate with CHI3L1, CHI3L2, GFAP, and C1q protein levels at any clinical stage." (PMID 32066474, 2020).